FDXACB1 (ferredoxin-fold anticodon binding domain containing 1)
Synonyms: LOC91893; hCG_2033039
Tractability: PROTAC: ubiquitination databases record sites on it.
Gene: Protein-coding gene on chromosome 11 (111,874,056 to 111,881,243, reverse strand). Ensembl gene ENSG00000255561.
Subcellular location (Human Protein Atlas): Cytosol; Nucleoplasm
Gene Ontology:
Molecular function: protein binding; rRNA (uridine-N3-)-methyltransferase activity
Biological process: rRNA base methylation
Genetic constraint (gnomAD): Loss-of-function variants: 41 observed, 52.44 expected, observed/expected ratio (o/e) 0.78, 90% interval 0.61 to 1.01. The upper end of that interval is the gene's LOEUF score, 1.01, which puts it in group 4 of 6, group 1 being the genes least tolerant of losing a copy. Missense variants: 697 observed, 775.08 expected, observed/expected ratio (o/e) 0.9, 90% interval 0.84 to 0.96. Synonymous variants: 273 observed, 291.07 expected, observed/expected ratio (o/e) 0.94, 90% interval 0.85 to 1.04.
Homologues: Orthologues: chimpanzee FDXACB1 (99% identical), pig FDXACB1 (82% identical), rabbit FDXACB1 (81% identical), guinea pig FDXACB1 (77% identical), mouse Fdxacb1 (72% identical), zebrafish fdxacb1 (39% identical), tropical clawed frog fdxacb1 (39% identical). Paralogues in human: FARS2 (16% identical), FARSA (9% identical).